SHH (sonic hedgehog signaling molecule)
Diseases named in the same sentence as SHH in open-access papers (continued):
Sharing a sentence is not in itself a finding about the gene and the disease.
lung carcinoma (continued). "Western blot analysis indicated that SBE dose-dependently down-regulated the expression of SHH signal cascade members, eventually leading to the cell cycle arrests in lung cancer cells." (PMID 28507311, 2017). "SHH was up-regulated in a large fraction of colon and kidney cancers and in a sizeable fraction of lung cancers." (PMID 23940460, 2013). "At the same time, sonic hedgehog (SHH), a secreted ligand of the hedgehog-signaling pathway known to be overexpressed in lung cancer, has been shown to be necessary and sufficient to activate OLIG genes in oligodendrocytes." (PMID 17388669, 2007). "In addition, we observed a considerable increase in SHH protein expression in lung cancer tissues after osimertinib resistance compared with that in preresistant tissues." (PMID 39721017, 2025). "The SHH signal pathway plays a key role in the process of carcinogenesis and development, and its abnormal activation is closely related to the proliferation and differentiation of lung cancer stem cells (CSCs)." (PMID 35132349, 2022). "Importantly, the results revealed that SFN is a potent drug preventing lung cancer cell growth through regulating SHH signaling pathway and polycomb group molecule PHC3." (PMID 34424425, 2021). "To explore whether SFN inhibited self-renewal of lung CSCs through the SHH signaling pathway, we further investigated the expression of key components of the SHH signaling pathway in CD133+ lung cancer cells which were treated by SFN." (PMID 34424425, 2021). "Since the SHH pathway plays a critical role in the renewal of CSCs, blockade of SHH pathway has evolved as a promising therapy for various types of cancers including lung cancer." (PMID 34424425, 2021). "SHH expression is negatively correlated with tumor differentiation in lung cancer." (PMID 31979397, 2020). "SHH expression and activity has also been reported in lung cancers." (PMID 32108165, 2020). "EMT regulation is a complicated process; the SHH/Gli pathway may take part in at different levels, thus, the detailed mechanism involving SHH signaling regulating EMT process in lung cancer needs further investigation." (PMID 31931858, 2020). "The inhibition of SHH has a significant effect on the invasion and migration of lung cancer cells." (PMID 31898580, 2019). "Two SMO inhibitors GDC-0449 (GDC) and BMS-833923 (BMS) for downregulation of SHH signaling was applied to explore whether activation of SHH pathways is involved in growth and clonal expansion of lung cancer cells." (PMID 28507311, 2017). "Previously, various CSC markers and self-renewal proteins such as CD133, CD44, ALDH1, ESA, β-Catenin, and SHH were found to be overexpressed in various cancers, including, but not limited to, pancreatic, head and neck cancer, prostate, breast, ovary, and lung cancer." (PMID 28122356, 2017). "In this study, we have demonstrated that the SHH signaling pathway was abnormally activated in lung CSCs, suggesting that the hyperactive SHH signaling may regulate the expression of stemness genes in lung cancer and play an important role in self-renewal and progression of lung CSCs." (PMID 34424425, 2021). "To accurately determine the expression level of the SHH/DUSP13B/p‐STAT3 axis in osimertinib‐resistant lung cancer tissues, we collected 10 pairs of clinical lung cancer tissue specimens before and after osimertinib resistance and conducted IHC staining." (PMID 39721017, 2025). "Prior studies have shown that targeting key points in the Hedgehog pathway, such as SHh, SMO, and GLI, can suppress lung cancer cell proliferation, enhance lung cancer cell apoptosis, and enhance drug sensitivity in drug-resistant lung cancer cells." (PMID 41444284, 2025). "Further, the SHH cascade and its executor GLI1 are aberrantly overexpressed in both CSCs and DDP-resistant lung cancer cells." (PMID 37149646, 2023).
lung carcinoma (continued). "We and other groups have previously found that the key transcription factor of the SHH pathway, GLI1, is upregulated and serves as a therapeutic target in lung cancer specimens; however, genetic alterations were rarely detected." (PMID 37149646, 2023). "Deregulated Sonic Hedgehog (SHH) pathway facilitates the initiation, progression and metastasis of NSCLC, confers drug resistance against targeted therapy and renders a lung cancer therapeutic interference option to cancer patients with poor prognosis." (PMID 28507311, 2017). "Alteration in PTCH expression does not affect oncogenic functions of Hedgehog cascade driven by SHH, SMO, and GLI1 in lung cancer cells." (PMID 28507311, 2017). "The levels of the Hh signaling components, SHH, PTCH1, and GLI1 were significantly reduced in CDO-depleted lung cancer cells compared with the scrambled control." (PMID 25369201, 2014). "Moreover, our study highlights the clinical relevance of these findings, demonstrating the increased expression of SHH, p‐STAT3, and GLI1 proteins in postosimertinib‐resistant lung cancer tissues, along with decreased DUSP13B expression." (PMID 39721017, 2025). "Further studies show that the SHH signal pathway may be regulated by CGRP on the proliferation and differentiation of lung cancer cells." (PMID 35132349, 2022). "Furthermore, this study revealed that SHH signaling pathway and PHC3 worked together in lung CSCs and that aberrant activation of these signals promoted the tumorigenesis and progression of lung cancer." (PMID 34424425, 2021). "Considering that SHH is activated by FAP overexpression in A549 adenocarcinoma and SK-MES-1 SCC lung cancer lines, it can be inferred that FAP might play an indirect role in the EMT process through SHH/GLI regulation." (PMID 34068501, 2021). "SHH was described to target INSM1 and promote the progress of lung cancer." (PMID 33282942, 2020). "We next analyzed the expression levels of canonical SHH signaling components—such as PTCH1, PTCH2, SMO, SUFU, and GLI1 proteins—in cultured human lung cancer cells (H1299, A549, HCC827, and H1975) and normal human lung fibroblasts (MRC-9 and WI38) by western blot analysis." (PMID 31783569, 2019). "Deregulated Sonic Hedgehog (SHH) pathway facilitates the initiation, progression, and metastasis of Non-small cell lung cancer (NSCLC), confers drug resistance and renders a therapeutic interference option to lung cancer patients with poor prognosis." (PMID 28507311, 2017). "The data disclose a new GLI1 stimulation pathway independent of the SHH/PTCH/SMO cascade and offer new insights into the stemness-related malignancy of lung cancer cells." (PMID 37149646, 2023). "As no prior report on the relationship between SHH and PHC3 in lung cancer existed, we employed a further study expression of PHC3 in siRNA-Shh transfected cells." (PMID 34424425, 2021).
bladder cancer (19 papers, 2012 to 2025). "STIL silencing induces PC assembly, prevents G0/G1 phase cells transfer to the G2/M phase, inhibits SHH signalling and causes cell proliferation and growth inhibition in bladder cancer cells." (PMID 37101292, 2023). "In ex vivo experiments, tissue microarray analysis of human bladder cancer specimens revealed a positive association of ROC1 expression with the SHH pathway activity." (PMID 33499884, 2021). "To validate the role of the loss of SHH induced by hypermethylation in the determination of the molecular subtype of human bladder cancer, we examined 10 muscle-invasive urothelial carcinoma samples derived from patients." (PMID 31036156, 2019). "Our analysis of primary human bladder cancer samples for the expression and associated methylation status of SHH was consistent with our findings from the murine BBN model of bladder cancer." (PMID 31036156, 2019). "Our results revealed that PC loss caused by IFT88 silencing could promote SHH signalling pathways activated in bladder cancer cells and uncontrolled cell proliferation." (PMID 37101292, 2023). "Similarly, in bladder cancer, it was reported that DNA hypermethylation of the CpG shore of the SHH gene caused the loss of the SHH gene and resulted in invasive urothelial carcinoma." (PMID 35563709, 2022). "As the basal subtype of human urothelial carcinoma is the most aggressive form of bladder cancer, associated with lower median overall survival, we sought to determine whether the SHH expression level was associated with clinical outcome in human bladder cancer patients." (PMID 31036156, 2019). "Bromodomain-4 protein (BRD4) is upregulated in bladder cancer tissues and cells, where it enhances the migration and invasion of cancer cells by positively regulating the sonic hedgehog (SHH) signaling pathway." (PMID 40635786, 2025). "The aberrant activation of the SHH signaling pathway exhibits significant heterogeneity in bladder cancer, characterized primarily by dysregulated activation of the Gli transcription factor family (particularly Gli3) and imbalance in non-coding RNA regulation." (PMID 41438986, 2025). "The SHH pathway is a critical signaling pathway in a variety of diseases, such as asthma, gastrointestinal system, preeclampsia, bladder cancer, and brain injury." (PMID 33343302, 2020). "Accordingly, the activation of the Sonic Hedgehog (SHH) signaling, known to contribute to bladder cancer progression and other tumors, is regulated by two receptors: The Patched and Smo." (PMID 32932969, 2020). "As an example, GALNT1 (a glycotransferase highly expressed by BCMab1+/CD44+ bladder CSCs) can stimulate the Hedgehog signaling through O-linked glycosylation of SHH, thus promoting CSC self-renewal in bladder cancer." (PMID 32932969, 2020). "Recent studies in bladder cancer suggest that secreted SHH functions to activate the release of stromal derived paracrine cues that promote epithelial differentiation of tumor cells." (PMID 31134896, 2019). "To further confirm the requirement for Hh/BMP signaling feedback in the subtype determination of human bladder cancer, we performed xenograft transplantation of a human bladder cancer cell line that was engineered to express shRNA targeting SHH or BMPR1A." (PMID 31036156, 2019). "One study has shown that basal subtype bladder cancer cells expressing sonic hedgehog signaling molecule (SHH), a vertebrate homolog of Drosophila hedgehog, are capable of regenerating all cell types within the urothelium, suggesting they are CSCs." (PMID 31137841, 2019). "In these tumors, we observed higher expression of SHH and downstream SHH targets, and higher expression of the SHH gene has been proposed to restrain bladder cancer progression." (PMID 31619281, 2019). "The expression pattern of SHH protein was examined in 160 patients with bladder cancer using immunohistochemistry (IHC)." (PMID 27454254, 2016).
bladder cancer (continued). "Recent findings revealed a constitutive activation of the SHH pathway in several malignancies including bladder cancer." (PMID 27454254, 2016). "SHH showed marked overexpression in bladder cancer compared with normal tissue (P<10−5), with a median expression level of 78.0 (range 0.22–721.6)." (PMID 22361633, 2012). "We also measured the SHH mRNA levels in six bladder cancer cell lines: HTB2, HTB4, HTB9, CRL1472, CRL1749, and CRL2169." (PMID 22361633, 2012). "The abnormal activation of the SHH pathway is primarily mediated through the following mechanisms: microRNA miR-7-5p is significantly downregulated in bladder cancer, where it directly binds to the 3’ untranslated region of Gli3 to inhibit its protein expression." (PMID 41438986, 2025). "As accumulating evidence suggests an essential role of hedgehog signaling in tumor cell proliferation, in this study, we explored the underlying molecular mechanisms by which ROC1 regulates the sonic hedgehog (SHH) pathway in bladder cancer using in vitro and in vivo experiments." (PMID 33499884, 2021). "Under this scenario, loss of SHH expression due to hypermethylation leads to the decreased expression of stromal BMP, which in turn stimulates the formation of the basal subtype of human bladder cancer, with poor clinical outcomes." (PMID 31036156, 2019). "We here investigated the clinical and pathological significance of SHH in bladder cancer." (PMID 27454254, 2016). "Further research is needed to investigate the functional significance of SHH in bladder cancer." (PMID 27454254, 2016). "SHH protein was overexpressed in 46 % of bladder cancer patients." (PMID 27454254, 2016). "Therefore, based on the expression of SHH, making timely intervention may be one of the primary preventions for bladder cancer." (PMID 35004540, 2021). "This study successfully identified a subset of bladder cancer stem cells that respond to GALNT1 siRNA and SHH inhibitors, providing a potential strategy for prevention and targeted treatment for recurrent bladder cancer." (PMID 35903544, 2022). "SHH signaling promotes epithelial to mesenchymal transition (EMT) and lymph node invasion in bladder cancer and hypoxia-induced up-regulation of cancer stem cell genes and EMT in cholangiocarcinoma." (PMID 31835472, 2019). "SHH overexpression was found in 96% of NMIBC and 52% of MIBC samples, as well as in two bladder cancer cell lines." (PMID 22361633, 2012). "Furthermore, AURKA depletion could reverse the malignancy phenotype, PC disassembly, and SHH signalling activation induced by STIL overexpression in BLCA cells, suggesting that STIL regulation for PC is dependent on AUKRA in bladder cancer." (PMID 37101292, 2023).
melanoma (19 papers, 2009 to 2026). A malignant, usually aggressive tumor composed of atypical, neoplastic melanocytes. "The high levels of IHH in HAS3-EVs were surprising, given that most of the reported studies on melanoma and other cancers have largely implicated the role of SHH in the process." (PMID 31820036, 2020). "In this study, mutational analysis together with immunoenzymatic quantification of SHH argues for a ligand-dependent autocrine mechanism as the prevalent way for the activation of the Hh cascade in melanoma." (PMID 41596411, 2026). "Immunoenzymatic analysis of soluble SHH in the cell culture medium evidenced an intense production of this factor by melanoma cells, proving the autocrine mechanism for the observed activation of the corresponding signaling." (PMID 41596411, 2026). "Confirming a ligand-dependent mechanism for abnormal Hh activation in melanoma cells, the circulating level of SHH was tendentially higher in patients compared to normal individuals." (PMID 41596411, 2026). "The integration of molecular, spectroscopic, and imaging data provides a comprehensive perspective on how silencing of KLF4, SHH, and HIF1α affects melanoma CSCs." (PMID 40854961, 2025). "In this study, we aimed to investigate how silencing of the KLF4, SHH, and HIF1α genes affects the cytoskeletal structure and biochemical characteristics of melanoma CSCs." (PMID 40854961, 2025). "This study demonstrates that silencing KLF4, SHH, and HIF1α in melanoma CSCs leads to coordinated changes in cytoskeletal structure, molecular composition, and cell morphology, reflecting a loss of stem-like properties." (PMID 40854961, 2025). "SHH-GLI signaling directly stimulates melanoma cell proliferation and survival, and blocking this pathway has an inhibitory effect on the stemness phenotype." (PMID 40806546, 2025). "Evidence indicates that the Hh pathway is crucial for the oncogenic characteristics of melanoma, SHH-GLI signaling regulates the proliferation and survival of human melanoma." (PMID 39611156, 2024). "Together, these results establish a strong correlation between the activation of SHH and the Gli pathway during melanoma progression." (PMID 37240209, 2023). "The normal skin tissues showed few of these positive cells, and the number of SHH-, Gli1-, and Gli2-positive cells per mm2 was significantly higher in the melanoma tissues than in the normal skin tissues (p < 0.05)." (PMID 37240209, 2023). "Before analyzing the mouse model of tumor bone destruction using skin-derived B16 mouse melanoma cells, a screening analysis of Sonic Hedgehog (SHH) signaling was performed using skin melanoma resection specimens without bone involvement (n = 37)." (PMID 37240209, 2023). "Pharmacologic inhibition of BRAFV600E in human melanoma cell lines resulted in decreased expression of GLI1 thus demonstrating interaction of SHH-GLI and MAPK pathways." (PMID 23935925, 2013). "Such spectacular effects of SHH signaling inhibition on tumor growth were also observed in other cancers such as human cholangiocarcinoma and melanomas." (PMID 20015350, 2009). "Investigation of circulating SHH levels revealed a modest increase in melanoma patients’ blood." (PMID 41596411, 2026). "Notably, we observed strong significant correlations between SHH and Gli1 (p < 0.0001) and between SHH and Gli2 (p < 0.0001) in the immunohistochemical-staining melanoma samples." (PMID 37240209, 2023). "In our study the expression of the SHH-GLI signaling pathway target GLI1 could be detected in 18 human melanoma cell lines and normal human melanocytes at mRNA level demonstrating the activity of this signaling pathway in human melanoma cell lines in vitro." (PMID 23935925, 2013). "Thus, the SHH inhibitors show effectiveness in Melanoma treatment." (PMID 38886736, 2024). "The increased release of SHH following SMO inhibition suggests a finely tuned regulatory mechanism within this signaling pathway, underscoring its significance in melanoma biology." (PMID 41596411, 2026).
melanoma (continued). "The Hedgehog (SHH-GLI) pathway, known for its essential role in embryogenesis and adult tissue homeostasis, is also involved in the maintenance of tumor stem cells in melanoma." (PMID 40806546, 2025). "In the present study, the silencing of HIF1α, SHH, and KLF4 in melanoma CSCs resulted in marked alterations in cell morphology, cytoskeletal organization, and molecular profile." (PMID 40854961, 2025). "In this study, we employed an integrated, multi-scale approach to investigate how melanoma CSCs respond to siRNA-mediated silencing of three key regulatory genes: KLF4, SHH, and HIF1α." (PMID 40854961, 2025). "It has been shown that the SONIC HEDGEHOG (SHH)-GLI and MAPK signaling pathway regulate cell growth in many tumors including melanoma and interact with each other in the regulation of cell proliferation and survival." (PMID 23935925, 2013). "Inhibition of SHH-GLI pathway by the novel small molecule inhibitor of smoothened NVP-LDE225 was followed by inhibition of cell growth and induction of apoptosis in human melanoma cell lines, interestingly with both BRAFV600E and BRAFWild Type status." (PMID 23935925, 2013). "We demonstrate that both standard SHH-GLI inhibitor cyclopamine and the novel more specific inhibitor of smoothened NVP-LDE225 reduce the GLI1 promoter activity, induce G1 cell cycle arrest, and induce apoptosis in human melanoma cell lines." (PMID 23935925, 2013). "Finally, we conclude that inhibition of SHH-GLI signaling pathway in human melanoma by the specific smoothened inhibitor NVP-LDE225 could have potential therapeutic application in human melanoma even in the absence of BRAFV600E mutation and warrants further investigations." (PMID 23935925, 2013). "Moreover, the concentration of SHH dose-dependently augmented in the presence of the SMO antagonist, arguing for an intrinsic tight modulation of the signaling by melanoma cells and the endeavor to counteract its suppression imposed by pharmacological treatment." (PMID 41596411, 2026). "Moreover, others showed that oncogenic RAS-induced melanomas in transgenic mice express GLI1 and require SHH-GLI signaling in vitro and in vivo and that endogenous RAS-MEK and AKT signaling regulates the nuclear localization and transcriptional activity of GLI1 in melanoma." (PMID 23935925, 2013).